EOLA2 (endothelium and lymphocyte associated ASCH domain 2)
Synonyms: CXorf40B
Tractability: No criterion of Open Targets' tractability assessment is met for any kind of drug.
Gene: Protein-coding gene on chromosome X (149,929,527 to 149,938,831, reverse strand). Ensembl gene ENSG00000197021.
Gene Ontology:
Cellular component: mitochondrion
Homologues: Orthologues: chimpanzee EOLA2 (96% identical), macaque EOLA2 (92% identical), macaque EOLA1 (82% identical), rat Eola2 (78% identical), dog EOLA1 (78% identical), mouse Eola1 (75% identical). Paralogues in human: EOLA1 (99% identical).